CLDN4 (claudin 4)
Diseases named in the same sentence as CLDN4 in open-access papers (continued):
Sharing a sentence is not in itself a finding about the gene and the disease.
Darier disease (1 paper, 2023). Darier disease (DD) is a keratinization disorder characterized by the development of keratotic papules in seborrheic areas and specific nail anomalies. "The objective of this study was to characterize the immunohistochemical staining patterns of claudin-4 in various acantholytic disorders, namely, Hailey–Hailey disease, Darier disease, Grover disease, acantholytic acanthoma, warty dyskeratoma, pemphigus vulgaris (PV), and pemphigus foliaceus." (PMID 38534263, 2023).
dermatitis (1 paper, 2016). An inflammatory process affecting the skin. "Th17 cells have been shown to infiltrate the skin lesions of AD, particularly during the acute phase of dermatitis, which suggested that IL-17 produced from Th17 cells decreases TJ function by inhibiting the synthesis of ZO-1, claudin-1, and claudin-4 proteins in AD." (PMID 27588419, 2016).
ductal carcinoma in situ (1 paper, 2013). "As in the few cases harboring foci of flat atypia, atypical ductal hyperplasia showed strong claudin-4 expression, along with the majority of the ductal carcinoma in situ samples." (PMID 23657508, 2013).
E. coli infection (1 paper, 2013). "In addition, induced claudin-4 expression by E. coli infection with a weakened TJ barrier has been reported in the bladder epithelium in mice." (PMID 23626786, 2013).
eczema (1 paper, 2023). "The claudin-4 staining pattern in eczema is identical to that of normal skin." (PMID 38534263, 2023). "Notably, claudin-4 staining in eczema exhibited markedly weak to negative expression in lesional area (the stratum spinosum with spongiosis) compared with non-lesional skin (the stratum granulosum) where moderate staining was observed." (PMID 38534263, 2023).
endometrial endometrioid adenocarcinoma (1 paper, 2013). A primary endometrial adenocarcinoma composed of neoplastic cells that form complex glandular patterns associated with budding and branching of the neoplastic glands. "The expression of claudin-4 in endometrial endometrioid adenocarcinoma (EEC) and normal human endometrial tissue was determined using immunohistochemistry and real-time PCR." (PMID 23599806, 2013).
enteropathy (1 paper, 2023). "Intestinal biopsies from severely undernourished children with enteropathy also showed a reduced expression of the tight junctions claudin-4 and E-cadherin, although the molecular mechanism relating undernutrition to changes in paracellular proteins remains unclear." (PMID 37892398, 2023).
epithelial dysplasia (1 paper, 2013). "The primary morphological features of epithelial dysplasia are cellular atypia, abnormal differentiation, and disorganized mucosal architecture; these changes are potentially associated with elevated claudin-4 expression." (PMID 23822740, 2013).
epithelial ovarian tumor (1 paper, 2016). "Claudin-4 is a transmembrane protein expressed at high levels in the majority of epithelial ovarian tumors, irrespective of subtype, and has been associated with tumor cells that are both chemoresistant and highly mobile." (PMID 27724921, 2016).
Glucose intolerance (1 paper, 2020). Glucose intolerance (GI) can be defined as dysglycemia that comprises both prediabetes and diabetes. "Taken together, these data show that Cldn4 deletion in adult male islets is associated with the glucose intolerance and compromised islet FS observed." (PMID 31562747, 2020). "If a similar Ca+2 metabolic disorder compromises β‐cell function, glucose intolerance should occur in both sexes of Cldn4−/− mice, but in this case, glucose intolerance was only detected in males." (PMID 31562747, 2020).
gluten intolerance (1 paper, 2020). "Increased expression of toll-like receptor 2 (TLR-2) and 4 (TLR-4), claudin 4 (CLD-4), and TNF-α has been shown by different groups in subjects with self-reported gluten intolerance." (PMID 33297984, 2020).
goiter (1 paper, 2024). Enlargement of the thyroid gland usually caused by lack of iodine in the diet, hyperthyroidism, or thyroid nodules. "Only goiters showed negative claudin-1 and positive claudin-4 staining, similar to those reported in normal thyroid tissues." (PMID 39458944, 2024).
hematoma (1 paper, 2025). A hematoma is a collection of blood from a vascular structure into an extravascular space. "MAT improved neurological performance, reduced hematoma volume and brain edema, and restored blood-brain barrier integrity through upregulation of tight junction proteins (ZO-1, Occludin, Claudin-4)." (PMID 41400019, 2025).
hydatidiform mole (1 paper, 2019). A gestational trophoblastic disorder characterized by marked enlargement of the chorionic villi, hyperplasia of the villous trophoblastic cells and hydropic changes. "The role of claudin-4 in human placenta is highlighted by the observation that its expression increases in hydatidiform moles and in maternal diabetes." (PMID 31569528, 2019).
hypopharyngeal cancers (1 paper, 2018). Carcinoma, predominantly squamous cell, arising from the epithelial cells of the hypopharynx. "Interestingly, our previous study in patients with oropharyngeal or hypopharyngeal cancers uncovered that the HGRE values are associated with the expression of some protein biomarkers including VEGF, GLUT-1, Claudin-4, and c-Met37." (PMID 30089896, 2018).
intestinal-type carcinoma (1 paper, 2025). "CLDN4 is highly expressed in differentiated intestinal-type carcinoma." (PMID 40687428, 2025).
invasive lobular carcinomas (1 paper, 2008). "Second, although no previous study has examined LCIS, several studies have examined expression of claudin 4 in invasive lobular carcinoma." (PMID 18954444, 2008). "In two of these four invasive lobular carcinomas, claudin 4 was also underexpressed, whereas in the other two expression in the invasive lobular carcinoma was at the same level as that seen in normal mammary epithelium." (PMID 18954444, 2008). "The one study that compared labelling to that of the normal duct epithelium reported down regulation of claudin 4 in two of two cases of invasive lobular carcinoma." (PMID 18954444, 2008). "Two studies reported intact claudin 4 expression in invasive lobular carcinoma; however, these studies did not compare expression with the normal duct epithelium, and used as little as 10% labelling as a criterion for positivity." (PMID 18954444, 2008). "Our results show that such an approach may not be applicable to LCIS or to invasive lobular carcinoma, because these lesions typically underexpress claudin 4 relative to normal breast epithelia." (PMID 18954444, 2008).
ischemia (1 paper, 2021). A hypoperfusion of the BLOOD through an organ or tissue caused by a PATHOLOGIC CONSTRICTION or obstruction of its BLOOD VESSELS, or an absence of BLOOD CIRCULATION. "Immunofluorescence imaging demonstrated qualitatively more visible claudin-4 in the membrane of recovered intestine treated with LA when compared to untreated, ischemia-injured intestine after 240 minutes of recovery." (PMID 33886649, 2021). "There were no statistical differences in cytoplasmic claudin-4 when comparing LA-treated tissues to untreated ischemia-injured tissues after recovery (Claudin-4/β-actin densitometry ratio of 0.75 ± 0.05 in LA-treated tissues vs. 0.81 ± 0.06 in untreated ischemia-injured tissues, NS)." (PMID 33886649, 2021).
kidney stones (1 paper, 2024). "In this study, CLDN1 expression was found to be increased in patients with a history of recurrent kidney stones and to be highly positively correlated with CLDN4, CLDN7 and CLDN14 and moderately correlated with CLDN2 and CLDN8." (PMID 39345805, 2024).
liver disease (1 paper, 2021). "For example, claudin-1 has been shown to be upregulated in advanced liver disease and HCC, and differential claudin-4 expression facilitates distinguishing between these two forms of cancer at the molecular level." (PMID 34338154, 2021).
lobular carcinoma (1 paper, 2021). "In addition, the expression of Cldn-4 was found to be increased in several pathological tissues with impaired barrier function, while decreased in other pathological tissues such as lobular carcinoma, suggesting that the expression of Cldn-4 is versatile and tissue dependent." (PMID 34884896, 2021).
lymphocytic colitis (1 paper, 2024). Microscopic colitis characterized by the accumulation of lymphocytes in the colonic epithelium and lamina propria. "In addition, the expression of proteins Cldn4 and Cldn8 has been shown to decrease in lymphocytic colitis." (PMID 38255781, 2024).
lymphoma (1 paper, 2024). A malignant (clonal) proliferation of B- lymphocytes or T- lymphocytes which involves the lymph nodes, bone marrow and/or extranodal sites. "Differential diagnosis was performed via immunohistochemistry (IHC), showing a loss of BRG1 and claudin-4, SALL4 expression, CD34, SMARCAB1, and negative lymphoma markers." (PMID 38542211, 2024).
malnutrition (1 paper, 2018). Inadequate nutrition resulting from poor diet, malabsorption, or abnormal nutrient distribution. "Decreased serum levels of claudin-4 were found in malnutrition states." (PMID 30259344, 2018).
Menière’s disease (1 paper, 2017). "Further we showed that the dDAVP/V2R- mediated translocation of cytosolic Claudin 4 into TJs is a mechanism capable to regulate the paracellular barrier and permeability properties of the ES epithelium associated with Menière’s disease." (PMID 28374851, 2017). "Our results indicate a high relevance of Claudin 3 and Claudin 4 as important paracellular barrier molecules in the ED and ES epithelium with potential involvement in the pathophysiology of Menière’s disease." (PMID 28374851, 2017). "Further we showed that Claudin 4 in the ES is a target of arginine-vasopressin (AVP), a hormone elevated in Menière’s disease." (PMID 28374851, 2017).
metastatic squamous cell carcinoma (1 paper, 2021). A squamous cell carcinoma which has spread from its original site of growth to another anatomic site. "BAP1-positive/claudin-4-negative expression was observed almost only in MPM with epithelioid features, while a single case of BAP1/claudin-4 negative metastatic squamous cell carcinoma from the anal region was observed." (PMID 34070888, 2021).
multiple sclerosis (1 paper, 2020). A progressive autoimmune disorder affecting the central nervous system resulting in demyelination. "Here, we found that these data are relevant to human disease since CLDN4 is also expressed by reactive astrocytes, with stronger CLDN4 labeling intensity at the Glia Limitans, in active cortical lesions from multiple sclerosis patients." (PMID 33253145, 2020). "We have previously found that reactive astrocytes express tight junctions, notably CLDN4, under inflammatory conditions in a mouse model of multiple sclerosis (EAE)." (PMID 33253145, 2020). "The expression of CLDN4 by astrocytes has only been identified in mouse models of CNS inflammation (acute CNS inflammation model (stereotactic injection of the pro-inflammatory cytokine IL-1β and model of multiple sclerosis: EAE MOG35-55)." (PMID 33253145, 2020).
NUT carcinomas (1 paper, 2021). "NUT carcinomas show frequent reactivity to epithelial markers (various cytokeratins and rarely Claudin-4), SOX2, and MYC antibodies." (PMID 34898574, 2021).
odontogenic cyst (1 paper, 2022). A cyst in the jaw that arises from tissues of tooth development. "Every type of odontogenic cyst had low expression of claudin-4, but claudin-1 and -7 were expressed in every odontogenic cyst." (PMID 34808689, 2022). "High claudin-1 expression was shown in COCs, DCs, and RCs, while low expression of claudin-4 was shown in every odontogenic cyst." (PMID 34808689, 2022).
ovarian serous cystadenocarcinoma (1 paper, 2013). A malignant serous cystic epithelial neoplasm arising from the ovary. "EGF was found to downregulate claudin-3 in mucinous ovarian carcinoma cell lines and claudin-4 in ovarian serous cystadenocarcinoma by inducing the degradation of these proteins with also changes in the structure and function of TJ via the MEK/ERK or PI3K/AKT signaling pathway." (PMID 23685873, 2013). "Additionally, in ovarian serous cystadenocarcinoma cell lines, EGF was found to downregulate the cytotoxic effects of CPE via claudin-4." (PMID 23685873, 2013).
papillary thyroid carcinoma (1 paper, 2024). "In The Cancer Genome Atlas cohort, claudin-1 and claudin-4 were overexpressed in papillary thyroid cancer compared to normal thyroid tissues." (PMID 39458944, 2024).
papilloma (1 paper, 2013). A benign epithelial neoplasm that projects above the surrounding epithelial surface and consists of villous or arborescent outgrowths of fibrovascular stroma. "We also noticed that lactation-type alteration was negative for claudin-4 and, amazingly, within the papilloma present in the study, claudin-4 expression was confined to the surface epithelia, while the bulk and inner layer were negative." (PMID 23657508, 2013).
peptic ulcer disease (1 paper, 2020). A digestive system disease characterized by discontinuation in the inner lining of the gastrointestinal (GI) tract because of gastric acid secretion or pepsin. "ZO-1 expression is decreased whereas claudin-4 is increased in H. pylori infected individuals indicating that damage to the gastric epithelial barrier function may be important in the pathogenesis of H. pylori peptic ulcer disease." (PMID 32161586, 2020).
pituitary adenoma (1 paper, 2023). "SLC2A1, CLDN4, LAMC2, S100A4, and ITGB3 were significantly correlated with the invasiveness of pituitary adenoma (P<0.05)." (PMID 36936141, 2023).
pneumococcal infection (1 paper, 2015). Infections with bacteria of the species streptococcus pneumoniae. "In this study, we showed that claudin-4-targeting using C-CPE elicited PspA-specific systemic and respiratory antibody responses that were sufficient to induce protection against pneumococcal infection." (PMID 26018248, 2015).
poisoning (1 paper, 2008). A condition or physical state produced by the ingestion, injection, inhalation of or exposure to a deleterious agent. "Both claudin-4 and claudin-3 (to a lesser extent) function as receptors for Clostridium perfringens enterotoxin (CPE), the virulence factor responsible for the symptoms of C. perfringens strain A food poisoning." (PMID 18648369, 2008).
polycystic ovary syndrome (1 paper, 2025). A disorder that manifests as multiple cysts on the ovaries. "Elevated testosterone levels in women with the endocrine disorder polycystic ovary syndrome (PCOS) influence the integrity of tight junctions in the endometrial epithelium by decreasing Cldn4 and occludin." (PMID 40867502, 2025).
preeclampsia (1 paper, 2019). Preeclampsia is a hypertensive disorder of pregnancy that is characterized by new-onset hypertension with proteinuria presenting after 20 weeks of gestation, and depending on mild or severe forms may initially present with severe headache, visual disturbances, and hyperreflexia. "The change observed in the chorionic villi cannot be attributed to the preeclampsia present in two of the ZIKV-infected donors, because the placentae of ZIKV-infected women without preeclampsia also exhibited a reduced claudin-4 expression." (PMID 31569528, 2019). "Finally, by Western blot, we previously observed that the amount of claudin-4 in the chorionic villi does not vary with preeclampsia." (PMID 31569528, 2019).
respiratory infections (1 paper, 2021). "Cldn-4 and 18 are highly expressed in airway tissues, yet the roles of these claudins in respiratory infections have not been clarified." (PMID 34702961, 2021).
sarcomatoid mesothelioma (1 paper, 2023). A diffuse malignant mesothelioma arising from the pleura and less often the peritoneum. "In contrast, the SMs were all negative for Claudin-4 and showed a BAP1 loss in 56.1% (23/41) of the cases, varying from 53.6% (15/28) of sarcomatoid mesotheliomas to 61.5% (8/13) of desmoplastic mesotheliomas." (PMID 36673059, 2023).
serous carcinomas (1 paper, 2013). "In addition, although more than 70% of high grade serous carcinomas express abundant amounts of CLDN3 and CLDN4, the site of origin of such tumors also remains in some doubt." (PMID 23805314, 2013). "Since the normal ovarian surface epithelium does not express either of these proteins, if serous carcinomas arise from this epithelium then a fraction must undergo a mesenchymal-to-epithelial transition (MET) during which the expression of CLDN3 and CLDN4 is up-regulated." (PMID 23805314, 2013).
sinusitis (1 paper, 2017). An acute or chronic inflammatory process affecting the mucous membranes of any sinus cavity. "CLDN-1 and CLDN-4 were downregulated in the sinusitis and NPs, whereas no change of CLDN-7 was observed in sinusitis or NPs." (PMID 28883651, 2017).
Sjogren syndrome (1 paper, 2021). An autoimmune disorder in which immune cells attack and destroy the glands that produce tears and saliva. "In Sjogren’s syndrome, IL-17 secreted by infiltrating lymphocytes disrupts the integrity of the tight junction barrier by downregulating claudin-4 and ZO-1 expression in submandibular glands." (PMID 35069523, 2021).
skin tumors (1 paper, 2013). "The data indicate that alterations found for Cldn-1, Cldn-4, ZO-1, and JAM-A are common for UV-induced skin tumors while the frequent loss of Ocln appears as specific for SCC." (PMID 23390516, 2013). "Looking for explanations for the common alterations of Cldn-1, Cldn-4 and ZO-1 identified in the various skin tumors, we hypothesized that chronic UV exposure might induce some of these changes." (PMID 23390516, 2013). "Because the alterations for Cldn-1, Cldn-4, and ZO-1 were observed in all UV- promoted skin tumors and a broader localization of Ocln was frequent in all tumor entities except for SCC, we wondered whether these alterations could also be identified in chronically sun-exposed skin." (PMID 23390516, 2013).
synovial sarcoma (1 paper, 2023). "Moreover, the Claudin-4 expression in the epithelial component of a biphasic lesion should also raise the possibility of biphasic synovial sarcoma." (PMID 36673059, 2023).
thoracic tumor (1 paper, 2021). "Typical immunohistochemical features for SMARCA4-deficient undifferentiated thoracic tumor is the lack of claudin 4 expression and low or absent keratin immunostaining, in addition to the loss of SMARCA4 (BRG-1)." (PMID 33968782, 2021).
thymic tumors (1 paper, 2023). "In conclusion, our findings, for the first time, estimated the expression of thymic cortical (β5t, PRSS16, and cathepsin V) and medullary epithelial markers (AIRE, CD40, and claudin-4) in differential diagnosis, Masaoka-Koga stage, histological classification, and prognosis of thymic tumors." (PMID 36797681, 2023).
thyroid tumor (1 paper, 2024). A benign or malignant neoplasm affecting the thyroid gland. "This article aimed to analyze the expression of claudin-1 and claudin-4 in various thyroid tumors." (PMID 39458944, 2024).
urinary tract infection (1 paper, 2024). "In the control group, the majority of the top 20 DEGs were associated with the epithelial cells, including epithelial barrier‐related genes (CLDN4, KRT19, and KRT18), and SLPI, a key gene reported to be localized to bladder epithelial cells and protect against urinary tract infection in mouse model." (PMID 38414668, 2024).